ATG7 (autophagy related 7)
Diseases named in the same sentence as ATG7 in open-access papers (continued):
Sharing a sentence is not in itself a finding about the gene and the disease.
ileitis (4 papers, 2015 to 2023). "Loss of autophagy via crossing to mice with deletion of Atg7 in the intestinal epithelial cells (Atg7/Xbp1ΔIEC), resulted in unresolved ER stress and a worsening of ileitis compared to Xbp1ΔIEC mice." (PMID 37443813, 2023). "In mouse models, decreased expression levels of Atg5, Atg7, or Atg4B generated abnormal Paneth cell functions, and in CD-like ileitis, deficiency of Atg16L1 also altered Paneth cell morphology." (PMID 35408838, 2022). "Complete knockout of Atg3, Atg5, Atg7, or Atg16L1 is lethal in mice, and impairment of either Atg7 or Atg16L1 results in severe CD-like transmural ileitis." (PMID 35408838, 2022). "Dysfunctions in either unfolded protein response factor, X‐box binding protein 1 (XBP1), or autophagy (ATG16L1 or ATG7) in IECs result in the reciprocal compensatory, and severe spontaneous ileitis develops if both mechanisms are defective." (PMID 29941542, 2018). "Interestingly, spontaneous ileitis observed in Xbp1ΔIEC mice is converted into severe CD-like transmural ileitis when both mechanisms, ER stress and autophagy, are compromised (Atg7/Xbp1ΔIEC and Atg16L1/Xbp1ΔIEC double transgenic mice)." (PMID 26221063, 2015).
lymphoma (4 papers, 2015 to 2024). A malignant (clonal) proliferation of B- lymphocytes or T- lymphocytes which involves the lymph nodes, bone marrow and/or extranodal sites. "In lymphoma, LncHOTAIR overexpression promoted the progression of cancer via regulating the hsa-miR-6511b-5p/ATG7 axis." (PMID 39135979, 2024).
non-alcoholic fatty liver disease (4 papers, 2018 to 2025). "A recent whole-exome sequencing study in individuals with non-alcoholic fatty liver disease (NAFLD) or HCC identified ATG7 loss-of-function variants that impair autophagy and promote p62 accumulation, ballooning, and inflammation." (PMID 40437287, 2025). "Remarkably, in non-alcoholic fatty liver disease patients, hepatic expression of JMJD3, ATG7, LC3, and ULK1 is substantially decreased." (PMID 32042044, 2020).
osteoarthritis (4 papers, 2023 to 2025). A noninflammatory degenerative joint disease occurring chiefly in older persons, characterized by degeneration of the articular cartilage, hypertrophy of bone at the margins and changes in the synovial membrane. "A similar phenomenon was found in a recent study where METTL3 regulated autophagy by affecting the stability of ATG7 transcripts in a m6A-dependent manner, thereby affecting synovial cell senescence in osteoarthritis." (PMID 39893158, 2025). "Osteoarthritis synoviocytes also display increased levels of N6-methylation of ATG7 mRNA, resulting in decreased protein levels." (PMID 40493419, 2025). "In a destabilization of the medial meniscus (DMM)-induced mouse osteoarthritis model, tissue immunofluorescence technique similarly indicated a decrease in chondrocyte autophagic activity in OA, including ATG7, Beclin-1, and LC3." (PMID 41013182, 2025).
osteoporosis (4 papers, 2020 to 2024). A condition of reduced bone mass, with decreased cortical thickness and a decrease in the number and size of the trabeculae of cancellous bone (but normal chemical composition), resulting in increased fracture incidence. "ATG7 and superoxide dismutase 2 are involved in the pathogenesis of osteoporosis, and their expression levels correlated in osteoporotic mice and osteoporosis-free mice." (PMID 38553562, 2024). "Deletion of Atg7 in osteoclast attenuated hyperactivation of osteoclast and osteoporosis induced by estrogen withdrawal or glucocorticoid exposure in mice." (PMID 36678499, 2022). "Surprisingly, deletion of Atg7 in the hematopoietic system enhanced iron activity in the HSPCs, which is often related to iron overload‐induced osteoporosis." (PMID 32212304, 2020). "This will ultimately lead to a reduced osteoporosis in the Atg7‐deleted mice, weakening the reliability of the Atg7‐deleted mice for use as a negative control for hematopoietic‐specific rescue effect in the osteoporotic model mice." (PMID 32212304, 2020).
pancreatic ductal adenocarcinoma (4 papers, 2020 to 2025). An infiltrating adenocarcinoma that arises from the epithelial cells of the pancreas. "While Atg5 and Atg7 are well established core autophagy genes, the role of Unc-51-like kinase 1 (ULK1)—a key autophagy initiator—remains poorly understood in pancreatic ductal adenocarcinoma (PDAC)." (PMID 41408407, 2025).
α-synucleinopathy (4 papers, 2020 to 2023). "Dysregulation of other key autophagic molecules like LC3, autophagy-related protein 7 (ATG7), or mammalian target of rapamycin (mTOR) is also a characteristic feature of α-synucleinopathies." (PMID 38203531, 2023). "In rodent α-synucleinopathy models, promoting autophagy by expressing BECN1, ATG7, LAMP2A or treatment with rapamycin reduces α-synuclein levels and ameliorates pathological disease markers." (PMID 33556113, 2021).
acute kidney injury (3 papers, 2019 to 2024). Sudden and sustained deterioration of the kidney function characterized by decreased glomerular filtration rate, increased serum creatinine or oliguria. "In terms of autophagy, conditional proximal tubule-specific KO mice for Atg5 or Atg7 display enhanced renal injury compared to wild-type mice in response to induced acute kidney injury (AKI) or chronic kidney disease (CKD)." (PMID 35805186, 2022). "Selective tubular cell Atg5 and Atg7 knockout mice develop more severe tubular cells damages and acute kidney injury (AKI) after ischemia-reperfusion injury." (PMID 30654583, 2019).
cerebral palsy (3 papers, 2020 to 2024). A group of disorders affecting the development of movement and posture, often accompanied by disturbances of sensation, perception, cognition, and behavior. "The gene variant and abnormal expression of ATG5 and ATG7 were also existed strong association with cerebral palsy patients." (PMID 34661876, 2022).
chronic obstructive pulmonary disease (3 papers, 2019 to 2022). A chronic and progressive lung disorder characterized by the loss of elasticity of the bronchial tree and the air sacs, destruction of the air sacs wall, thickening of the bronchial wall, and mucous accumulation in the bronchial tree. "In the case of chronic obstructive pulmonary disease (COPD), caused mainly by smoking, exosomes from lung cells consist of miR-210, which helps reduce Atg7 expression, blocks self-eating, and induces myofibroblast growth and scarring of tissue." (PMID 36364116, 2022). "In the case of chronic obstructive pulmonary disease (COPD), a very frequent pathology mainly caused by cigarette smoking, EVs derived from human lung tissue contain miR-210, which blocks Atg7 expression, preventing autophagy and causing myofibroblast differentiation and fibrosis." (PMID 30759880, 2019). "Similarly, the expression of ATG proteins (LC3-II, ATG4, ATG5-ATG12, ATG7) as well as the number of autophagic vacuoles was also increased in lung tissue from patients with chronic obstructive pulmonary disease (COPD)." (PMID 34019141, 2021).
Cognitive impairment (3 papers, 2017 to 2025). Abnormal cognition is characterized by deficits in thinking, reasoning, or remembering. "Thus, knockdown of Atg7 inhippocampal neurons leads to similar cognitive deficits as observed in FXS, suggestingthat dysfunctional autophagy in hippocampal neurons plays a critical role in thisprocess." (PMID 40909783, 2025).
COVID-19 (3 papers, 2024 to 2026). A disease caused by infection with severe acute respiratory syndrome coronavirus 2. "Our partial correlation analysis showed that vitamin D had strong positive correlations with two autophagy markers (ATG7 and BECN1), suggesting a close link between vitamin D and autophagy in COVID-19." (PMID 38783947, 2024). "The group with severe/critical COVID-19 had more abnormalities in many laboratory indicators, including lower levels of autophagy markers (BECN1 and ATG7) and vitamin D, and higher levels of inflammatory markers (TNF-α and IL-1β)." (PMID 38783947, 2024). "Our study showed that the levels of vitamin D and two autophagy markers (ATG7 and BECN1) were lower in patients with severe/critical COVID-19 than in those with mild/moderate COVID-19." (PMID 38783947, 2024).
cutaneous melanoma (3 papers, 2021 to 2025). A primary melanoma arising from atypical melanocytes in the skin. "We then performed Kaplan–Meier survival analysis after stratifying these 424 cutaneous melanoma patients by ATG7 3′ UTR length." (PMID 38302465, 2024).
depression (3 papers, 2022 to 2025). "The expression of autophagy‐related genes (Atg5, Atg7, Atg12, Becn1, Mmp9, Fkbp5, and Map1lc3b), which are reported to be upregulated in the brains of MDD patients, were examined in the hippocampus and midbrain of control and depression model mice." (PMID 39715728, 2025).
encephalitis (3 papers, 2017 to 2023). An acute inflammatory process affecting the brain parenchyma. "In post-mortem brains from HIV-1 patients with encephalitis, levels of autophagy proteins such as Beclin 1, ATG5, ATG7, and LC3-II were significantly increased, as compared to the brains from HIV-1 positive patients without HIV-1 encephalitis or uninfected controls." (PMID 33669846, 2021). "Notably, several key autophagic factors, such as BECN1, ATG5, ATG7, and LC3-II, were found to be elevated in the postmortem brains of HIV-1 encephalitis patients compared to HIV-1 patients without encephalitis." (PMID 37445802, 2023).
endothelial dysfunction (3 papers, 2022 to 2025). In vascular diseases, endothelial dysfunction is a systemic pathological state of the endothelium (the inner lining of blood vessels) and can be broadly defined as an imbalance between vasodilating and vasoconstricting substances produced by (or acting on) the endothelium. "The observed downregulation of placental ATG7 expression subsequent to fetal CPB is intricately associated with endothelial dysfunction." (PMID 41060356, 2025). "ATG7 expression in the placenta was downregulated after fetal CPB in sheep, which was related to endothelial dysfunction." (PMID 41060356, 2025).
glomerulopathy (3 papers, 2019 to 2024). "The genetic deletion of Atg7 in the ECs of Atg7flox/flox;Tie2-Cre mice accelerated aging-related glomerulopathy and tubulointerstitial fibrosis." (PMID 39199133, 2024). "Specific ablation of autophagy gene Atg5 result in albuminuria and glomerulopathy in aging mice and podocyte deletion of Atg7 exaggerate ADR-induced podocyte injury." (PMID 34580283, 2021). "In Podo-Atg7, podocyte-specific knock out mice, doxorubicin treatment resulted in podocyte injury, glomerulopathy, and proteinuria." (PMID 30734886, 2019).
head and neck squamous cell carcinoma (3 papers, 2014 to 2023). A squamous cell carcinoma that arises from any of the following anatomic sites: lip and oral cavity, nasal cavity, paranasal sinuses, pharynx, larynx, and salivary glands. "There are currently few studies in the literature regarding ATG7 expression, mainly in head and neck squamous cell carcinomas." (PMID 37173926, 2023). "In fact, alterations of ATG7 gene were detected in TCGA Head and Neck Squamous Cell Carcinoma samples as we analyzed the data set using the cBio Cancer Genomic Portal (cBioPortal)." (PMID 24599075, 2014).
heart failure (3 papers, 2021 to 2025). Inability of the heart to pump blood at an adequate rate to meet tissue metabolic requirements. "In heart failure, overexpression of ATG7 reversed the cardiomyocyte apoptosis and autophagy inhibition mediated by miR-129-5p mimics." (PMID 41221017, 2025).
hepatocellular adenoma (3 papers, 2012 to 2022). A benign epithelial neoplasm arising from the hepatocytes. "For example, notable p62 accumulation was observed in hepatocellular adenomas derived from liver-specific Atg7 knockout mice." (PMID 35725745, 2022).
Hyperinsulinemia (3 papers, 2018 to 2022). An increased concentration of insulin in the blood. "During IR and hyperinsulinemia, the autophagy activity and transcription levels of genes such as Atg7 are inhibited; this is closely related to transcriptional regulation mediated by the downstream signaling molecule FoxO1." (PMID 36147338, 2022). "Next, we found that the expression of major components of the autophagy process, including Beclin-1, Atg7, Atg3, Atg12-Atg5, free Atg12, Atg16L1, and LC3II was not affected by hyperinsulinemia." (PMID 29719598, 2018).
liver disease (3 papers, 2018 to 2024). "In the McA-rh7777 cell culture, consistent with the previous study in rats, we observed an increase in Atg7, a gene involved in autophagy/lipophagy, a fundamental process involved in human liver disease." (PMID 36014938, 2022). "In this nomogram, factors such as the number of liver metastases and chemotherapy history did not impact prognosis while extra hepatic diseases emerged as the most influential prognostic factor, followed by the risk factors identified in our model—the genes CYP4F3 and ATG7." (PMID 38795162, 2024).
lung adenocarcinoma (3 papers, 2015 to 2022). A carcinoma that arises from the lung and is characterized by the presence of malignant glandular epithelial cells. "Immunohistochemistry assay results revealed that both NDC80 and ATG7 were upregulated in an array of lung adenocarcinoma samples, compared to normal tissues, and the expression of NDC80 was identified to be positively associated with the levels of ATG7." (PMID 36105209, 2022).
lupus (3 papers, 2013 to 2021). "Moreover, polymorphisms in IRGM have been linked to the multifactorial autoimmune disease systemic lupus erythematosus (SLE), as have polymorphisms in Atg5 and Atg7." (PMID 23577011, 2013).
malignant mesothelioma (3 papers, 2022 to 2024). A malignant neoplasm of the pleura or peritoneum, arising from mesothelial cells. "An experimental model demonstrated the activation of YAP caused by ATG7 deletion, which is an important transcription activator in malignant mesothelioma." (PMID 36831074, 2023). "However, high expression of ATG7 has been considered a promising prognostic tool for patients affected by malignant mesothelioma." (PMID 39131899, 2024). "In our recent research, ATG7's high expression represents a promising prognostic tool for patients with MPM76, thus it would be interesting to explore if there is an inverse correlation between ATG7 and YAP in malignant mesothelioma." (PMID 35654808, 2022). "In our recent research, ATG7’s high expression represents a promising prognostic tool for patients with MPM; thus, it would be interesting to explore whether there is an inverse correlation between ATG7 and YAP in malignant mesothelioma." (PMID 36831074, 2023).
metastatic disease (3 papers, 2020 to 2022). "Of note, however, while the overall incidence of metastatic disease is reduced in Atg7 hemizygous animals, those that do undergo metastasis present PDAC lesions in the same secondary organs—liver, lungs, and diaphragm—as those wild-type for Atg7." (PMID 35867735, 2022). "Out of the 46 patients without metastatic disease, ATG7 L-IRS was found only in 13/46 non metastatic UMs (28.3%), while 33/46 (71.7%) had ATG7 H-IRS (Fisher’s exact test, p = 0.026)." (PMID 33330070, 2020).
oncocytomas (3 papers, 2022 to 2025). "Contrary to our assumption, we observed an upregulation of ATG7 in oncocytomas, with the non-reducing gel displaying ATG7-LC3 complex in RO but not in the normal kidney." (PMID 40806782, 2025). "Therefore, we investigated if ATG7 function was compromised in oncocytoma by using non-reducing WB to determine if ATG7 was actively forming functional complexes." (PMID 40806782, 2025).
prostate tumor (3 papers, 2019 to 2024). "Delayed Pten-deficient prostate tumor progression in both castrate-resistant and castrate-naïve cancers and autophagy-deficient phenotype is attributed to Atg7 deficiency." (PMID 36589680, 2022). "ATG7 has also been reported to facilitate the transcription of OCT4, promoting prostate tumor initiation, self-renewal, and drug resistance." (PMID 30871066, 2019).
psoriasis (3 papers, 2024). An autoimmune condition characterized by red, well-delineated plaques with silvery scales that are usually on the extensor surfaces and scalp. "We used myeloid cell-specific autophagy-related gene 7 (Atg7)-deficient mice and determined the effect of autophagy deficiency in myeloid cells on neutrophilia and disease pathogenesis in an imiquimod-induced psoriasis mouse model." (PMID 38704587, 2024). "To explore the direct role of autophagy in myeloid cells in the pathogenesis of psoriasis, we developed a model of psoriasis using Atg7fl/fl;LysM-Cre mice, which selectively exhibit a deficiency of the autophagy gene Atg7 in myeloid cells such as neutrophils and macrophages." (PMID 38704587, 2024). "However, AMPK was found to promote both autophagy and skin inflammation in the psoriasis mouse model via the ULK1/ATG7 signaling pathway." (PMID 38690268, 2024). "In line with our results, IMQ was shown to reduce levels of autophagy-related proteins, including phosphorylated ULK-1, ATG-7, and LC3A/B, in murine models of psoriasis-like inflammation." (PMID 39337618, 2024).
sarcopenia (3 papers, 2021 to 2023). Progressive decline in muscle mass due to aging which results in decreased functional capacity of muscles. "Defective autophagy has been reported in sarcopenia, in particular, Atg7 KO mice have been characterized as an animal model of sarcopenia." (PMID 37372945, 2023). "Finally, age-related declines in autophagy-related proteins LC3 (MAP1LC3A) and ATG7 have previously been reported, and these declines are thought to contribute to sarcopenia." (PMID 33669246, 2021).
acute pancreatitis (2 papers, 2017 to 2022). An acute inflammatory process that leads to necrosis of the pancreatic parenchyma. "Mice deficient for pancreatic Atg7 developed acute pancreatitis, which progressed to chronic pancreatitis." (PMID 28703808, 2017).
Arthritis (2 papers, 2022 to 2025). Inflammation of a joint. "In our study, the administration of CFA dramatically lowered the articular gene expression of ULK-1, Beclin-1, and ATG-7 as compared to control rats, leading to significant downregulation in the autophagy process, supporting the hypothesis of autophagy involvement in hindering arthritis severity." (PMID 40350466, 2025). "WJR significantly reduced toe swelling, arthritis scores, and expression of miRNA-146a and autophagy genes (ATG5, ATG7, ATG12, Beclin1, LC32, and Bcl2)." (PMID 36440364, 2022). "We noted that treatment of the rat model with WJR resulted in a significant reduction in toe swelling, arthritis severity, expression of miRNA-146a, and expression of autophagy genes (ATG5, ATG7, ATG12, Beclin1, LC32, and Bcl2)." (PMID 36440364, 2022).
chronic kidney disease (2 papers, 2022 to 2024). Impairment of the renal function secondary to chronic kidney damage persisting for three or more months. "Loss of ATG5 or ATG7 in renal epithelium can lead to chronic kidney disease in mice." (PMID 38373978, 2024).
chronic myelogenous leukemia (2 papers, 2023). "Moreover, blocking autophagy using pharmacological blockers (CQN), or silencing of ATG5 and ATG7, significantly enhanced the killing of imatinib-resistant cells in chronic myelogenous leukemia." (PMID 37761021, 2023). "In chronic myeloid leukemia (CML), inhibition of autophagy by silencing ATG7 or ATG4B curbs the expansion of CML CD34+ stem/progenitor cells." (PMID 37886168, 2023).